INS (insulin)
Diseases named in the same sentence as INS in open-access papers (continued):
Sharing a sentence is not in itself a finding about the gene and the disease.
Insulin resistance (continued). "Recent studies also indicated that aspirin might be an insulin sensitizing agent and they may be used to reverse hyperglycemia, hyperinsulinemia, and dyslipidemia by sensitizing insulin signaling and improving insulin resistance." (PMID 28807030, 2017). "These may include hormonal profiles, blood glucose, hemoglobin A1C, insulin, C-peptide, or parameters for insulin resistance." (PMID 27936468, 2017). "Endocrine disruptors deregulate pancreatic islet β-cell function, development of peripheral insulin resistance, insulin production, β-cell mass (compensatory hyperplasia/hypertrophy of β-cells) and impaired insulin output, insulin signaling, increasing β-cell apoptosis." (PMID 29064461, 2017). "In addition to mortality, reduced serum 25(OH)D was shown to correlate with insulin resistance, obesity, aberrant phasing of insulin responses to glucose loading, glucose intolerance, fasting hyperglycemia, or also T2DM." (PMID 28134804, 2017). "There is also increasing evidence that podocyte insulin responses may be negatively regulated in situations of systemic insulin resistance." (PMID 28852804, 2017). "We have shown that mice fed on a low-protein diet in adolescence, followed by a high-fat diet during adulthood, develop glucose intolerance, insulin resistance, and reduced insulin secretion, compared to those fed on a high-fat diet during the whole experimental period." (PMID 28951790, 2017). "Diabetes can be caused by the pancreas not producing insulin (type 1 diabetes (T1DM)) or by insulin resistance (type 2 diabetes (T2DM))." (PMID 28811863, 2017). "Increased plasma insulin, indicative of insulin resistance, was observed in the 24wHFDO and this was likely to have stimulated increased glucose uptake into adipocytes and vascular smooth muscle via an insulin-dependent glucose transporter (GLUT4), which is not present on the endothelium." (PMID 28376507, 2017). "In addition to their roles as signaling molecules regulating cell growth, apoptosis, and vesicular trafficking, ceramides can also contribute to systemic insulin resistance by disrupting intracellular insulin signaling." (PMID 28486481, 2017). "Typified by a reduced ability of insulin to elicit action at cells throughout the body, as well as general hyperinsulinemia, insulin resistance is at the heart of most cardiometabolic disorders, such as hypertension, atherosclerosis, dyslipidemia, cardiomyopathy, and more." (PMID 28304347, 2017). "By detecting decreased insulin sensitivity at an early stage, management and feeding strategies could be developed to prevent the development insulin resistance." (PMID 28617863, 2017). "Additionally, their results found that significantly elevated blood Gal3 levels in obese patients were positively correlated with homeostatic model assessment—insulin-resistance index values—and that Gal3 also induced insulin resistance in human muscle cells." (PMID 28758131, 2017). "Insulin resistance in T2DM might be combined with reduced insulin secretion and defective responsiveness of insulin receptors." (PMID 28811863, 2017). "Hence, a reduced insulin resistance or increased insulin sensitivity after metformin can also increase the sensitivity of the vasculature for the relaxants by stimulating multiple pathways including NO and EDHF44–46." (PMID 28887562, 2017). "However, in insulin resistance, IR-B preferential activation by insulin results in IRS1/2-mediated increase in the activity of the p85α regulatory subunit of PI3K (PI3K p85α), which inhibits Akt thus reducing NO generation." (PMID 29104874, 2017). "Furthermore, there were some reports about the relationship between AGEs and insulin secretion and insulin resistance by using the ELISA method; however, there were few reports about the exact quantitation of AGEs by using LC-MS/MS methods." (PMID 28695132, 2017).
Insulin resistance (continued). "We evaluated the patients' fasting plasma glucose, insulin, homeostasis model assessment of insulin resistance index (HOMA-IR), thyroid-stimulating hormone (TSH), free thyroxine (FT4), antithyroperoxidase antibodies (TPO-Ab), antithyroglobulin antibodies (Tg-Ab), and thyroid ultrasound." (PMID 29412382, 2017). "This suggests that maternal obesity may impair DHA’s ability to participate in insulin metabolism and may contribute to insulin resistance." (PMID 28165405, 2017). "Despite slightly weaker or similar correlations with the lipid ratios as the L/A ratio, adiponectin together with estimated insulin sensitivity or insulin resistance, remained a predictor in the final model, suggesting effects on CV risk independent of associations with glucose metabolism." (PMID 28068986, 2017). "However, impaired insulin action in the liver leads to insulin resistance, characterized by an impaired insulin capacity to inhibit glucose production." (PMID 29065507, 2017). "However, the mice exhibited reduced brain glucose uptake and decreased insulin signaling, indicative of brain insulin resistance." (PMID 28710347, 2017). "It is therefore possible that local complement activation within the adipose tissue may affect insulin sensitivity of the adipose tissue and contribute to the reduced peripheral insulin resistance observed in the LBW subjects after overfeeding." (PMID 28450702, 2017). "As already discussed (Section 3), palmitate induces insulin resistance in insulin-responsive cells independently of neutrophils, but the latter are recruited to adipose tissue and promote diet-induced insulin resistance by producing myeloperoxidase and other proinflammatory substances." (PMID 29081894, 2017). "Thus, disruption of hepatic insulin signaling results in fasting and postprandial hyperglycemia and the subsequent development of peripheral insulin resistance." (PMID 29286343, 2017). "High fat diet feeding is associated with the development of central obesity, insulin resistance, high circulating plasma insulin concentration and non-alcoholic fatty liver." (PMID 28578702, 2017). "In addition, while basal reactive oxygen species (ROS) level has positive effects on both insulin secretion in β-cells and insulin signaling, ROS overproduction is detrimental and can lead to insulin resistance." (PMID 28607631, 2017). "Higher intake of both beverages was significantly associated with lower insulin levels (p < 0.01); however, higher intake of LCSB was also associated with lower hemoglobin A1c (HbA1c) and lower homeostatic model assessment of insulin resistance (HOMA-IR) (p < 0.01)." (PMID 28837084, 2017). "In addition, irisin correlated positively with fasting insulin, homeostasis model assessment of insulin resistance (HOMA-IR), age, cholesterol ratio, and BMI in patients with gestational diabetes." (PMID 28658348, 2017). "At least in part, the deterioration in glucose tolerance in OR mice treated with the anti-LIF antibody was due to the development of insulin resistance, as determined by an insulin-tolerance test and the determination of the constant for glucose decay during the insulin tolerance test (kITT)." (PMID 28865476, 2017). "It is characterized by chronic hyperglycemia, altered insulin secretion, and insulin resistance." (PMID 28891932, 2017). "These molecular shifts were followed by a classic cascade of events leading to insulin resistance such as adipose tissue inflammation, increased macrophages' chemotaxis, impaired insulin downstream signalling along with insulin-induced glucose uptake, and increased lipolysis in affected adipocytes." (PMID 28194257, 2017). "Several additional conditions often accompanying the syndrome were also present: insulin resistance (increased plasma insulin), kidney damage (increased plasma creatinine and albuminuria) and inflammation (increased plasma levels of TNF-α and interleukin six (IL-6))." (PMID 28101123, 2017).
Insulin resistance (continued). "HF and HF + HG mice displayed glucose intolerance and insulin resistance, and had higher concentrations of serum insulin (0.34 ± 0.1 ng/ml in STD, 1.41 ± 0.3 ng/ml in HF, 0.69 ± 0.2 ng/ml in HG, and 1.53 ± 0.3 ng/ml in HF + HG mice; HF or HF + HG vs STD, p < 0.001)." (PMID 29180700, 2017). "Insulin resistance is associated with hyperinsulinemia and, although we did not measure circulating insulin levels, we found reduced insulin sensitivity and reduced glucose tolerance in HFD-fed subjects, particularly in males." (PMID 28706476, 2017). "However, the glucose decreasing effect of insulin is diminished when the insulin sensitivity of perirenal tissue is impaired, which results in insulin resistance and hyperinsulinemia." (PMID 29057818, 2017). "The influences of PA could be explained by its beneficial effects on body composition, including improving skeletal muscle insulin sensitivity and reduce insulin resistance." (PMID 29161331, 2017). "Therefore, we aimed to identify the in vivo ubiquitin-modified proteome (ubiquitome) in rat liver and determine changes in this ubiquitome under acute insulin stimulation and in high-fat diet-induced insulin resistance." (PMID 28329008, 2017). "However IF animals had increased serum concentrations of adiponectin (+92%) and reduced HOMA insulin resistance (−49%) compared to the high fat fed animals indicating improved hepatic insulin sensitivity with IF." (PMID 28106818, 2017). "Molecular and metabolic abnormalities in insulin action, such as peripheral tissues (muscle, liver, and adipose tissues) insulin resistance, together with minor defects in insulin secretion, can be clearly identified before the development of obesity or hyperglycemia." (PMID 28635632, 2017). "Under specific conditions, IL-6 may either decrease or enhance insulin resistance, as well as improve glucagon-like peptide-1-mediated insulin section." (PMID 29163354, 2017). "Also, increased body mass index and diastolic blood pressure as well as higher levels of glucose, insulin and insulin resistance were evident in men as compared to women." (PMID 28448601, 2017). "So far, no studies have addressed the question whether inhibition of the insulin/IGF-2/IR-A signaling by these approaches may provide benefits to patients with TC in the context of insulin resistance." (PMID 29184536, 2017). "Recent reports from our laboratories show that high-fat diet progressively reduces hepatic CEACAM1 level in C57BL/6J mice until it reaches >50% after 3 weeks, at which point, insulin clearance is impaired and hyperinsulinemia develops with attendant hepatic insulin resistance and steatohepatitis." (PMID 28184213, 2017). "T2DM is a highly prevalent and chronic metabolic disorder caused by insufficient insulin production from pancreatic islet β-cells in the setting of insulin resistance, with the inability of cells in muscle, liver, and fat to adequately respond to normal insulin levels." (PMID 28934129, 2017). "However, maintaining high plasma insulin concentrations for an extended period led to insulin resistance and glucose intolerance in these mice at 6 months old." (PMID 28951790, 2017). "Furthermore, some evidence indicates that TNF-α is an important player in the state of insulin resistance observed during obesity by interfering with insulin signaling." (PMID 28408969, 2017). "In this study, serum insulin level and insulin resistance index, HOMA-IR, in the HF group mice was significantly elevated compared to those of the LF group, while OXY supplementation alleviated them in high-fat diet-fed mice and reduced their levels to those of the LF mice." (PMID 28212343, 2017). "The fact that global population is becoming more obese due to the growing sedentary lifestyle and higher caloric intake results in an increase in insulin resistance (IR), which may be defined as reduced sensitivity to insulin in target tissues." (PMID 28184199, 2017).
Insulin resistance (continued). "The metabolic phenotype of PWS is different as compared to common obesity and some metabolic complications typically related to obesity, such as insulin resistance and reduced hepatic insulin extraction, are less severe than expected for the degree of fat accumulation." (PMID 28600576, 2017). "Interestingly, PHLDA1 is induced by IGF-1 and insulin upregulates IGF-1 receptors in conditions with insulin resistance, as in PCOS." (PMID 28068351, 2017). "The 4-week very-low calorie diet (VLCD, 800 kcal/day) induced a mean weight loss of 6.9 ± 1.9 kg accompanied by a reduction in HOMA-IR (Homeostasis model assessment-insulin resistance), fasting plasma glucose and insulin, plasma leptin, and leptin gene expression in subcutaneous adipose tissue." (PMID 28931850, 2017). "Our results indicated that the OVX-HFD and OVX-HFDD groups have increased serum N-MID-OT and TRAP levels accompanied by insulin resistance, although the consequences of insulin resistance for bone remain largely unknown." (PMID 28950016, 2017). "This interaction might be associated with RCC aggressiveness, as adiponectin knockout mice develop insulin resistance and accumulating evidence in humans indicates that adiponectin plays an important role in insulin dynamics." (PMID 28178338, 2017). "The aim of this study was to investigate whether a novel physiologically relevant marker, InsuTAG (fasting insulin × fasting triglycerides) can predict insulin resistance (IR) and metabolic syndrome (MetS)." (PMID 29123160, 2017). "High levels of circulating insulin due to insulin resistance or insulin treatment also result in reduced insulin-like growth factor binding protein (IGFBP), leading to increased insulin-like growth factor 1 (IGF-1), which has more potent anti-apoptotic and mitogenic effects than insulin." (PMID 29238337, 2017). "Since the FGF21’s improvement of insulin resistance is largely attributed to enhanced insulin action in the liver, we suggest that the EPO’s enhancement of BAT derived-FGF21 secretion contributes to the reduction of gluconeogenesis of liver in induced obese mice on a high-fat diet." (PMID 28288167, 2017). "Our working hypothesis is that fiber type-selective deficits in insulin-stimulation of AS160 on Thr642 and Ser588 underlies the fiber type-selective insulin resistance that we revealed in the current study." (PMID 29057943, 2017). "In the same line, feeding of ZDF rats for 7 weeks with a diet supplemented with a 5% of a soluble cocoa product enriched in cocoa fiber decreased blood glucose and insulin and, thus, insulin resistance measured as homeostasis model assessment of insulin resistance (HOMA-IR) index." (PMID 29088075, 2017). "However, Mfn2 activity in BAT contributes to insulin resistance, as Mfn2 excision in brown adipocytes, using Ucp1 promoter‐driven Cre, improves insulin sensitivity in obese mice." (PMID 28539390, 2017). "Insulin resistance is characterized by a suppressed insulin-stimulated glucose uptake by the cells, resulting from the impairment of intracellular insulin signaling pathways and disability to increase the amount of glucose transporters (GLUTs) in the cell membrane." (PMID 28236091, 2017). "Thus, increased insulin sensitivity to adipose tissues would be another mechanism of improving the insulin resistance in obesity." (PMID 28578702, 2017). "In addition, plasma SFRP4 levels were positively correlated with BMI (r = 0.259, P = 0.030), fasting insulin levels (r = 0.306, P = 0.010) and homeostasis model assessment of insulin resistance (HOMA-IR) values (r = 0.331, P = 0.005)." (PMID 29037197, 2017). "A major drawback, however, is that the results of OGTTs reflect a complex interplay between insulin secretion and insulin resistance, and this may affect the reproducibility of the results." (PMID 29216249, 2017).
Insulin resistance (continued). "In addition, leptolide (0.1 μM) counteracted palmitate-induced insulin resistance by augmenting by four-fold insulin-stimulated phosphorylation of PKB in HepG2 cells." (PMID 28914811, 2017). "Furthermore, studies in healthy elderly individuals and insulin-resistant offspring of parents with type 2 diabetes have demonstrated that repressed mitochondrial function may predispose these individuals to intramyocellular lipid accumulation and insulin resistance." (PMID 27981357, 2017). "Indirectly, metformin reduces insulin resistance, resulting in a reduction of circulating glucose and insulin levels, which may able to inhibit tumor growth." (PMID 29069850, 2017). "The effect of gut microbiota on peripheral insulin sensitivity begins at the level of the intestinal mucosa, as WD-induced insulin resistance is prevented by blocking live intestinal bacteria from translocating into the blood and tissues where they generate an inflammatory response." (PMID 28194099, 2017). "Recent studies suggest that bone may as well control insulin sensitivity given that the deletion of insulin receptor in osteoblasts conducts to insulin resistance and obesity." (PMID 28695134, 2017). "The defect in insulin delivery process via ECs contributes to insulin resistance." (PMID 28447033, 2017). "Consequently, increased serum insulin concentrations suggestive of insulin resistance were observed in the current studies." (PMID 27814245, 2017). "Notably, during the progression of insulin resistance to T2DM, the predominantly anabolic processes transition to predominantly catabolic processes, with the loss of insulin activity." (PMID 28574481, 2017). "We hypothesized that insulin levels, and particularly a measure of insulin resistance calculated from circulating insulin and glucose, would also have a significant impact on memory and memory-related brain activity." (PMID 28093279, 2017). "It is noteworthy that the inhibitory effect of fructose on FA oxidation in rat livers was amplified by co-administration of insulin, suggesting that it may be altered in the context of insulin resistance." (PMID 28878197, 2017). "TNF-α may induce insulin resistance through direct effects on the insulin signaling pathway, and thus participates in the pathogenesis of type 2 DM and obesity." (PMID 28426801, 2017). "Significant increases in serum insulin concentration, homeostasis model assessments of insulin resistance, luteinizing hormone, luteinizing hormone/follicle-stimulating hormone, fasting blood sugar, testosterone, and prolactin were observed in the case group compared to the controls." (PMID 29387827, 2017). "During the progression of obesity and insulin resistance, pancreatic islets initially increase β-cell mass and overproduce insulin; however, the ability of the β-cell to counteract an increased glucose load is short-lived and eventually pancreatic islets fail, giving rise to hyperglycaemia." (PMID 28442507, 2017). "In addition, insulin sensitivity and insulin resistance correlated with fasting serum insulin (P = 0.0001)." (PMID 29340122, 2017). "These molecular shifts were followed by a classic cascade of events leading to insulin resistance such as adipose tissue inflammation, increased macrophage chemotaxis, impaired insulin downstream signalling along with insulin-induced glucose uptake, and increased lipolysis in affected adipocytes." (PMID 29098064, 2017). "In another study with diabetic individuals, 60 g/day of almonds (20% of the total energy intake) for four weeks reduced serum insulin concentrations by 4.1% and the insulin resistance index (homeostasis model assessment, HOMA-IR) by 9.2% compared to the control group." (PMID 29207471, 2017). "Moreover, this activation can cause hepatic insulin resistance through activation of the c-Jun N-terminal kinase (JNK) pathway, which inhibits insulin signaling through inactivation and/or degradation of IRS-1." (PMID 28587303, 2017).